KLF2 (KLF transcription factor 2)
Diseases named in the same sentence as KLF2 in open-access papers (continued):
Sharing a sentence is not in itself a finding about the gene and the disease.
lung carcinoma (12 papers, 2018 to 2026). "For example, KLF2, a tumor suppressor pseudogene, was reduced in 57.5 % of lung cancer and associated with KLF2 hypomethylation and lymph node metastasis." (PMID 38560274, 2024). "In contrast to our findings, circ_0043256 has been reported as tumor-suppressive in lung cancer, acting through distinct axes (e.g., miR-1206/KLF2, miR-1252/ITCH, and multiple miRNA-mediated networks) to inhibit proliferation and growth." (PMID 41568058, 2026). "High KLF2 was involved in inhibition of energy metabolism, glutaminase activity, and reduction of intracellular l-glutamine level affected lung cancer growth." (PMID 38560274, 2024). "TIMP2 and KLF2 expression is reduced in lung cancer, and patients with decrease dexpression have a poorer outcome." (PMID 34497265, 2021). "Moreover, FOXF1 is also co-expressed in the CCP of the LC RNA-Seq datasets, along with seven of the most frequently dysregulated TFs (FOXM1, SOX17, TAL1, TCF21, TBX4, LMO2, and KLF2), suggesting its importance as a regulator of gene expression during lung cancer progression." (PMID 36661515, 2023). "In this paper, KLFs have been summarized via systematic reviews, with either a promoting (KLF4 ∼ KLF8, KLF15) or an inhibiting (KLF2 ∼ KLF6, KLK9 ∼ KLF12 and KLF17) roles, which should be useful to monitor lung cancer progression or understand its mechanisms." (PMID 38560274, 2024). "Two of the most frequently dysregulated transcription factors are co-expressed in lung cancer and PAH (FOXM1 and FOXF1), while the other six frequently deregulated transcription factors are co-expressed only in lung cancer (TCF21, SOX17, TAL1, LMO2, KLF2, and TBX4)." (PMID 36661515, 2023). "Additionally, LINC00511 was also demonstrated to downregulate the expressions of KLF2 and LATS2 by promoting the binding of LSD1 to the promoter regions of LATS2 and KLF2 in lung cancer cells." (PMID 32713253, 2020). "Up-regulating KLF2 could inhibit NSCLC cell proliferation, induce P15 and P21 expression to arrest the G0/G1 cell cycle and promote apoptosis, indicated that KLFs might be regulated through epigenetic alterations to target lung cancer." (PMID 38560274, 2024).
pulmonary hypertension (12 papers, 2020 to 2025). Increased pressure within the pulmonary circulation due to lung or heart disorder. "Recently, the development of pulmonary hypertension was reported to be associated with reduced KLF2 signalling, and KLF2-regulated EVs play important regulatory roles in vascular remodelling and vascular homeostasis." (PMID 35139878, 2022). "Furthermore, the upregulation of XIST represses expression of Kruppel-like factor 2 (KLF2), encoded on chromosome 19, in female pulmonary arterial endothelial cells, mimicking the repression of KLF2 observed in human pulmonary arterial hypertension." (PMID 34068984, 2021). "In a hypoxia-induced pulmonary hypertension model, Klf2 is activated by G-protein-coupled receptor-mediated Apelin signaling." (PMID 38985140, 2024). "Therefore, abnormal expression of KLF2 is closely related to pulmonary diseases, such as pulmonary hypertension, chronic obstructive pulmonary disease (COPD), and ALI." (PMID 32091104, 2020). "In addition, modulation of KLF2 showed therapeutic potential for pulmonary hypertension." (PMID 35181831, 2023). "Although a KLF2 mutation was suggested to be associated with pulmonary arterial hypertension (PAH), an inborn error in immunity (IEI) associated with KLF2 gene has not been reported." (PMID 36466816, 2022).
Arthritis (9 papers, 2014 to 2025). Inflammation of a joint. "Arthritis in KLF2 deficient animal model is dependent on IL-1β which in turn can be controlled by the NF-κβ pathway." (PMID 36466816, 2022). "In summary, these data confirm that the decreased level of KLF2 in arthritic monocytes and concomitantly increased levels of various inflammatory and arthritis-related molecules are associated with disease progression." (PMID 31426355, 2019). "KLF2 is associated with development of autoimmunity and arthritis." (PMID 36466816, 2022). "Moreover, methylated bovine serum albumin (mBSA) and IL-1β induced arthritis caused greater damage to cartilage and bones in KLF2 hemizygous mice compared to WT controls." (PMID 32477372, 2020). "This explains our finding of modest but significant elevated expression levels of IL-1, IL-6, CCL3, and MCP1 in the bone marrow cells of KLF2 heterozygous mice after induction of arthritis, which were associated with the formation of marginal erosions found in KLF2+/− mice." (PMID 31426355, 2019). "Furthermore, arthritis in KLF2 deficient animals is dependent on IL-1β." (PMID 36466816, 2022). "Compared with KLF2 WT mice, KLF2 knockout mice developed more severe paw swelling and synovitis after arthritis induced by K/BxN serum, and cartilage and bone erosion were significant, which aggravated the pathological changes of RA." (PMID 38546623, 2024). "KLF2 is thought to have a role in pathogenesis of autoimmunity and has a protective role in the K/BxN arthritis model in mice." (PMID 36466816, 2022). "We next assessed the effect of KLF2 hemizygosity on osteoclast precursor cells after K/BxN serum-induced arthritis development." (PMID 31426355, 2019). "We found markedly increased levels of MMP9 and MMP13 in KLF2−/− mice compared to KLF2+/+ mice after induction of arthritis." (PMID 31426355, 2019). "KLF2+/− mice developed severe paw swelling and joint inflammation after arthritis induction, whereas KLF2+/+ (WT) mice showed very mild paw and joint inflammation." (PMID 31426355, 2019). "We found that expression levels of IL-1β, IL-6, TNFα, CCL3 and MCP-1 molecules were significantly (p < 0.05) increased after induction of arthritis in the bone marrow of KLF2+/− mice compared to KLF2+/+ mice." (PMID 31426355, 2019). "As these molecules are all demonstrably important in the process of RA progression, we sought to determine how the expression levels of these molecules are changed upon induction of arthritis in KLF2+/− mice." (PMID 31426355, 2019). "After 7 days of arthritis induction, osteoclast precursor cells were harvested from the bone marrow of the KLF2+/− and KLF2+/+ mice." (PMID 31426355, 2019). "In the current study, we used K/BxN serum-induced arthritis models to investigate the role of KLF2 in disease progression using various genetic models of KLF2 in mice." (PMID 31426355, 2019). "Using KLF2 hemizygous mice we studied its role in methylated bovine serum albumin (mBSA) and IL-1β-induced arthritis conditions." (PMID 29125549, 2017). "Additionally, overexpressed KLF2 reduces arthritis, suggesting the important role of histone acetylation and autophagy controlled by KLF2 in bone resorption." (PMID 40153585, 2025). "Moreover, in a mouse arthritis model, the level of KLF2 in monocytes was reduced, which in turn promoted their differentiation into osteoclasts by activating autophagy." (PMID 37391422, 2023). "In M1-polarizing conditions, 65–79*SE was predicted to stimulate activation of pro-inflammatory, pro-RA upstream regulators, such as Stat3, Rel, Rela, Jun, Ctnnb1 and Hif1a, among others, and to inhibit anti-arthritis or anti-inflammatory regulators (e.g. Klf2, Xbp1, Foxp3)." (PMID 33510427, 2021). "In order to determine whether K/BxN serum-induced arthritis has any effects on KLF2 expression in monocytes, monocytes were isolated from C57BL/6 mice 7 days after induction of arthritis and q-PCR was performed to determine expression of various markers." (PMID 32477372, 2020).
Arthritis (continued). "Hence, these data support the assertion that monocyte-specific KLF2 is important in the regulation of K/BxN serum-induced arthritis." (PMID 31426355, 2019). "We further investigated whether K/BxN serum-induced arthritis exerts any effect on the expression level of KLF2 in the monocytes of bone marrow or peripheral blood in C57/BL6 mice." (PMID 31426355, 2019). "Due to the known roles of NF-κB in rheumatoid arthritis and the initial findings of anti-inflammatory effects of KLF2 in induced arthritic models, we hypothesized that KLF2 possibly reduce arthritis by negatively regulating NF-κB via the recruitment of PCAF." (PMID 29125549, 2017). "Furthermore, Klf2 haploinsufficiency in mice results in an exaggerated inflammatory response and more severe disease in arthritis models." (PMID 25099603, 2014). "The regulatory role played by KLF2 in the activation, differentiation, and function of monocytes was further confirmed using monocyte-specific conditional KLF2 knockout mice (in which ~90% reduction of KLF2 expression was observed) in a K/BxN serum-induced arthritis model." (PMID 31426355, 2019). "The morphological appearance of mouse joint inflammation with progressively severe arthritis in KLF2+/− mice revealed the inhibitory role of KLF2 in arthritic induction, which is further supported by the finding that inflammation was increased in KLF2 hemizygous mice." (PMID 31426355, 2019). "In order to evaluate effects of monocyte-specific KLF2 knockout on osteoclastic differentiation and resorptive activity, bone marrow cells were harvested from conditional KLF2−/− and KLF2+/+ mice after induction of arthritis." (PMID 32477372, 2020). "The role of KLF2 in monocytes was further confirmed in immunocompetent mice (C57BL/6 background) in which KLF2 level was significantly reduced in monocytes isolated from peripheral blood and bone marrow after induction of K/BxN serum-induced arthritis." (PMID 31426355, 2019). "Real-time PCR analysis revealed a significantly reduced level of KLF2 expression in monocytes either isolated from bone marrow (p < 0.005) or peripheral blood (p < 0.001) compared to the respective monocytes isolated from control mice without arthritis." (PMID 31426355, 2019).
Cirrhosis (9 papers, 2017 to 2024). A chronic disorder of the liver in which liver tissue becomes scarred and is partially replaced by regenerative nodules and fibrotic tissue resulting in loss of liver function. "Several studies have reported that KLF2 plays an important role in maintaining hepatic endothelial cell homeostasis and vascular integrity, and protects the liver from fibrosis or cirrhosis." (PMID 37386390, 2023). "While this endogenous response is ultimately ineffective, augmenting KLF2 activity by simvastatin treatment can lessen the vascular dysfunction in cirrhosis." (PMID 32268503, 2020). "In another setting – hepatic cirrhosis in rats – simvastatin (25 mg/k/d for 3 days) increased Klf2, eNOS and Nppc gene expression in hepatic sinusoidal endothelial cells." (PMID 32404888, 2020). "This evidence relates to the fact that Kruppel-like factor 2 (KLF2) is naturally expressed early in cirrhosis to prevent progression of the disease." (PMID 32268503, 2020). "And we also assessed the differential levels of KLF2 expressed in cirrhosis tissue and HCC tissue." (PMID 37386390, 2023). "Furthermore, miR-126 is also a potent modulator of VEGF signalling via KLF-2-dependent mechanisms, especially in the context of liver inflammation and cirrhosis." (PMID 30042823, 2018). "In the liver, the transcription factor KLF2 is induced early during progression of cirrhosis to lessen the development of vascular dysfunction; nevertheless, its endogenous expression results are insufficient to attenuate establishment of portal hypertension and aggravation of cirrhosis." (PMID 28293634, 2017). "Experimental models of cirrhosis have shown that, in vitro, beneficial effects of statins are directly exerted on LSEC through an overexpression of the transcription KLF2 induced by statins." (PMID 31882668, 2019). "In addition, we examined the expression distribution of SNAI1, ZEB2, and VIM, which are the top three markers exhibiting strong correlation with KLF2, in the GSE25097 dataset related to cirrhosis development." (PMID 37386390, 2023). "Therefore, we further analyzed the distribution of KLF2 expression in two datasets related with cirrhosis development, GSE 25097 and GSE 6764, to investigate the different expression of KLF2 in the tumor tissue compared to cirrhosis tissue." (PMID 37386390, 2023). "The disparity of our results between BDL and CCl4 models could be attributed to differences in the induction of cirrhosis and mainly to the stage of liver disease; while in the BDL model KLF2 expression is highly induced, in our CCl4 model it is not initiated yet." (PMID 28084470, 2017).
COVID-19 (9 papers, 2021 to 2024). A disease caused by infection with severe acute respiratory syndrome coronavirus 2. "Interestingly, the expression of KLF2 was decreased in the PBMC of individuals with the Delta COVID-19 variant." (PMID 39712003, 2024). "Lung fibroblasts due to COVID-19 have also been associated with KLF2." (PMID 37243274, 2023). "During COVID-19, the transcription factor KLF2, a master regulator of vascular homeostasis, is downregulated in ECs and was associated with COVID-19-associated EC dysfunction." (PMID 39281671, 2024). "This is in line with the normal anti-inflammatory role of KLF2, and its low expression can be partially responsible for the development of COVID-19 exacerbation." (PMID 39712003, 2024). "We observed that the gene and protein expression of kruppel-like factor 2 (KLF2), a master regulator of vascular homeostasis, was decreased in endothelial cells treated with serum from COVID-19 patients." (PMID 34253708, 2021). "Pharmacologic (atorvastatin and tannic acid) and genetic (adenoviral overexpression) approaches to augment KLF2 levels attenuated COVID-19-serum-induced increase in endothelial inflammation and monocyte adhesion." (PMID 34253708, 2021). "Here, we demonstrate that the expression of KLF2 was reduced and monocyte adhesion was increased in endothelial cells treated with COVID-19 patient serum due to elevated levels of pro-adhesive molecules, ICAM1 and VCAM1." (PMID 34253708, 2021). "Our data indicate that KLF2 depletion by KLF2 siRNA partially reverses atorvastatin mediated protective effects against COVID-19-serum-induced monocyte adhesion." (PMID 34253708, 2021). "IL-1β and TNF-α, two cytokines elevated in cytokine release syndrome in COVID-19 patients, decreased KLF2 gene expression." (PMID 34253708, 2021). "Our data indicate that KLF2 depletion by siRNA further aggravates COVID-19-patient-serum-induced monocyte adhesion to endothelial cell." (PMID 34253708, 2021). "It was speculated that drugs like atorvastatin that can induce KLF2 expression would improve EC functions of COVID-19-damaged ECs due to their anti-inflammatory and anti-thrombotic functions." (PMID 39281671, 2024). "Such treatment reduced KLF2 gene expression resulting in a depletion of this protein that further enhanced monocyte adhesion to endothelial cell due to the treatment with the serum from COVID-19 patients." (PMID 35409070, 2022). "In addition, KLF2 overexpression reversed COVID-19-patient-serum-induced eNOS gene and protein downregulation, indicating that SARS-CoV2-infection-induced cytokine storm disrupts endothelial homeostasis." (PMID 34253708, 2021). "Collectively, the present study implicates loss of KLF2 as an important molecular event in the development of COVID-19-induced vascular disease and suggests that efforts to augment KLF2 levels may be therapeutically beneficial." (PMID 34253708, 2021). "Finally, knockdown of KLF2 partially reversed the ameliorative effect of atorvastatin on COVID-19-serum-induced endothelial inflammation and monocyte adhesion." (PMID 34253708, 2021). "We next evaluated whether TNF-α, and IL-1β, two cytokines observed in COVID-19 patients, can decrease KLF2 gene expression." (PMID 34253708, 2021). "KLF2 plays a significant role in COVID-19 as SARS-CoV-2 significantly down-regulates KLF2 expression: COVID-19 patients have elevated serum levels of TNF-α and IL-1 and decreased KLF2 gene expression." (PMID 35409070, 2022). "Moreover, both KLF2 and FOS were downregulated in myeloid cells coming from individuals with severe Delta COVID-19." (PMID 39712003, 2024).
glioma (9 papers, 2015 to 2022). A benign or malignant brain and spinal cord tumor that arises from glial cells (astrocytes, oligodendrocytes, ependymal cells). "For instance, SNHG3 enhances the malignant behaviors of glioma through silencing Kruppel-like factor 2 (KLF2) and p21 protein (p21) via recruiting EZH2 to the promoter of KLF2 and p21." (PMID 33292213, 2020). "These experiments revealed that SNHG3 accelerates the malignancy of glioma by inhibiting transcription of KLF2 and p21." (PMID 33292213, 2020). "In addition, KLF2 and p21 were downregulated in glioma tissues." (PMID 33292213, 2020). "Additionally, KLF2 also mediates the expression of miR-126 in endothelial and glioma cells." (PMID 26406238, 2015). "For instance, the upregulation of DANCR promotes glioma progression via Wnt signaling 18, and SNHG3 promotes glioma development by suppressing the expression of KLF2 and p21 expression." (PMID 32913464, 2020).